MIR124-3 (microRNA 124-3)
Synonyms: hsa-mir-124a-3; hsa-mir-124-3; MIRN124-3; MIRN124A3; mir-124-3
Gene: MicroRNA gene on chromosome 20 (63,178,500 to 63,178,586, forward strand). Ensembl gene ENSG00000207598.
Gene Ontology:
Biological process: miRNA-mediated post-transcriptional gene silencing
Cellular component: RISC complex
Homologues: Orthologues: chimpanzee MIR124-3 (100% identical), macaque MIR124-3 (100% identical), pig MIR124-3 (100% identical), rat Mir124-3 (100% identical), tropical clawed frog MIR124-3 (84% identical), zebrafish dre-mir-124-4 (79% identical), mouse Mir124a-3 (78% identical), zebrafish dre-mir-124-1 (74% identical), zebrafish mir124-5 (67% identical), zebrafish mir124-6 (57% identical), Caenorhabditis elegans cel-mir-124 (51% identical), Drosophila melanogaster mir-124 (49% identical). Paralogues in human: MIR124-2 (84% identical), MIR124-1 (82% identical).